BRAF (B-Raf proto-oncogene, serine/threonine kinase)
Diseases named in the same sentence as BRAF in open-access papers (continued):
Sharing a sentence is not in itself a finding about the gene and the disease.
Insulin resistance (1 paper, 2020). Increased resistance towards insulin, that is, diminished effectiveness of insulin in reducing blood glucose levels. "But in general, circulating biomarkers of insulin resistance and adipokines were at most weakly associated with CRC risk, and not clearly associated with specific subtypes of CRC based on KRAS- and BRAF-mutations and MSI status of the tumor." (PMID 32210264, 2020).
intestinal tumors (1 paper, 2013). "Third, murine and human intestinal tumors with KRAS mutations are mostly MSI-stable or MSI-low, whereas BRAF mutant human tumors are frequently MSI-high." (PMID 23845441, 2013).
intracranial AVM (1 paper, 2019). "Thus, it seems likely that BRAF represents a second locus for which somatic mutations can cause intracranial AVM." (PMID 31891627, 2019). "We identified KRAS or BRAF mutations in 63% of the sporadic, intracranial AVM specimens we studied." (PMID 31891627, 2019). "Importantly, we provide the second example of a BRAF p.V600E mutation in an intracranial AVM and a novel BRAF mutation in a second intracranial AVM (p.Q636X)." (PMID 31891627, 2019).
intraductal papilloma (1 paper, 2025). An intraluminal papillary epithelial neoplasm arising within the ducts. "Although PIK3CA or AKT mutations are more common in breast intraductal papilloma, AKT1 E17 K mutation was detected in intraductal papilloma of minor salivary glands, and no genetic alterations (BRAF, PI3KCA etc.)were detected in salivary glands intraductal papilloma with previous reports." (PMID 40013097, 2025).
iris tumours (1 paper, 2020). "Another study on 19 cases showed a BRAF mutation in 47% of the iris tumours." (PMID 32998469, 2020).
leukocytosis (1 paper, 2025). "In the CBC, leukocytosis was observed more frequently in patients with MAP2K1 (33.3%) compared to BRAF mutations (14.3%)." (PMID 40692796, 2025).
Lymphatic Metastasis (1 paper, 2024). Transfer of a neoplasm from its primary site to lymph nodes or to distant parts of the body by way of the lymphatic system. "The malignant group before PSM was further divided into subgroups according to the BRAF V600E mutation and lymphatic metastasis (N stage), and the number of CTCs in different subgroups was compared." (PMID 38607590, 2024).
lymphoproliferative disorder (1 paper, 2023). "Introducing BRAF(V600E) in hematopoietic stem cells drives a hematological malignancy with much more aggressive pathology than that of human HCL, which in B cells does not have any lymphoproliferative disorder." (PMID 37543582, 2023).
melanosis (1 paper, 2022). "The keywords “primary acquired melanosis”, “metastasis” and “BRAF mutations” were most frequently emerged." (PMID 36059617, 2022).
metastatic prostate carcinoma (1 paper, 2021). A carcinoma that arises from the prostate gland and has spread to other anatomic sites. "The association between BRAF activation and enzalutamide resistance was confirmed in two metastatic prostate cancer patients harboring activating mutations in the BRAF gene, as both patients were unresponsive to enzalutamide." (PMID 34211036, 2021).
multiple keratoacanthomas (1 paper, 2024). "Eruptive melanocytic nevi and multiple keratoacanthomas are rare cutaneous conditions, often linked to drug-related toxicities but rarely reported simultaneously, particularly in cancer patients undergoing BRAF-targeted therapies." (PMID 39479087, 2024).
myeloid sarcoma (1 paper, 2018). A tumor mass composed of myeloblasts or immature myeloid cells. "NGS analysis of the myeloid sarcoma in this case showed a clonal, non V600E activating mutation in BRAF." (PMID 29463311, 2018).
myopericytoma (1 paper, 2024). A usually slow growing, subcutaneous nodular neoplasm arising from myopericytes. "Some researchers, including Mito and Sadow, have proposed that BRAF mutations may constitute a novel genetic anomaly in the pathogenesis of myopericytomas, along with related biomarkers." (PMID 38643070, 2024).
myositis (1 paper, 2025). "We present a case of a 68-year-old man who developed acute inflammatory demyelinating polyneuropathy (AIDP) with superimposed myositis following treatment of BRAF-wild type GIST with imatinib." (PMID 40959351, 2025).
Oculomotor apraxia (1 paper, 2024). Ocular motor apraxia is a deficiency in voluntary, horizontal, lateral, fast eye movements (saccades) with retention of slow pursuit movements. "Dabrafenib, another BRAF inhibitor, resulted in a case of PRES with Bálint’s syndrome—a triad of optic ataxia, oculomotor apraxia, and simultanagnosia." (PMID 38345654, 2024).
odontogenic cyst (1 paper, 2025). A cyst in the jaw that arises from tissues of tooth development. "Indeed, aberrations in the MAPK, Sonic Hedgehog (SHH), and WNT/β-catenin pathways are well documented in odontogenic cysts and tumors, with BRAF, PTCH1, and CTNNB1 representing the most frequently altered genes." (PMID 41364259, 2025).
oligodendroglial tumor (1 paper, 2018). Oligodendrogliomas are cerebral tumors that are differentiated from other gliomas on the basis of their unique genetic characteristics and better response to chemotherapy. "By additional molecular analyses, BRAF and FGFR1 gene alterations specific to each subgroup were identified: particularly, BRAF alterations in the astrocytic-like group 1 and FGFR1 alterations in group 2, oligodendroglial tumors." (PMID 30279357, 2018).
oncocytic neoplasm (1 paper, 2021). A usually benign neoplasm composed of large cells with abundant eosinophilic granular cytoplasm. "The most common gene mutations such as rat sarcoma gene (RAS), v-Raf murine sarcoma viral oncogene homolog B (BRAF), and Telomerase reverse transcriptase promoter gene (TERTp) mutations were described in HCC but always in lower frequency than in non-oncocytic neoplasms." (PMID 34248855, 2021).
osteonecrosis (1 paper, 2024). A none disease characterized by death of bone tissue due to a lack of blood supply. "However, data regarding BRAF expression levels and changes in steroid-induced osteonecrosis of the femoral head remain limited." (PMID 39926257, 2024).
osteoporosis (1 paper, 2025). A condition of reduced bone mass, with decreased cortical thickness and a decrease in the number and size of the trabeculae of cancellous bone (but normal chemical composition), resulting in increased fracture incidence. "The LASSO regression algorithm established an osteoporosis-related model, identifying six disease-related candidate core target genes (IGF1R, NR3C1, MAP3K1, BRAF, WNK4, CNR2)." (PMID 40692598, 2025). "Abnormal activation or inhibition of BRAF could directly interfere with osteogenesis, while WNK4, a kinase primarily regulating ion transport and cellular homeostasis, shows a strong binding affinity with TPhP, suggesting that TPhP may promote osteoporosis by disrupting ion balance." (PMID 40692598, 2025).
Palmoplantar keratoderma (1 paper, 2024). Abnormal thickening of the skin of the palms of the hands and the soles of the feet. "The proportion of patients from the BRAF inhibitor alone treatment group who had a high-grade CAEs compared with the BRAF and MEK inhibitor treatment group were 29.02% vs. 4.98% for palmoplantar erythrodysaesthesia syndrome and 19.86% vs. 6.98% for palmoplantar keratoderma." (PMID 39776585, 2024). "The proportion of patients from the BRAF inhibitor alone treatment group who had a high-grade CAE compared with the BRAF and MEK inhibitor treatment group were 29.02% vs. 4.98% for palmoplantar erythrodysaesthesia syndrome and 19.86% vs. 6.98% for palmoplantar keratoderma." (PMID 39776585, 2024).
Pan (1 paper, 2021). "We identified 36 high-frequent shared putative neoantigens derived from eight oncogenic driver mutations with more than 1% coverage of multiple cancer patients in the 9079 TCGA cohort, e.g. HLA-A*03:01_KIGDFGLATEK from BRAF_p.V600E with 5.60% (508/9079) in Pan-Cancer." (PMID 34113354, 2021).
papillary lung adenocarcinoma (1 paper, 2024). A morphologic variant of lung adenocarcinoma characterized by the presence of papillary structures. "The 5% BRAF-positive papillary lung adenocarcinoma might be metastatic TC." (PMID 39767631, 2024).
parotid gland carcinoma (1 paper, 2026). A primary or metastatic malignant neoplasm involving the parotid gland. "The “Genetic Biomarkers” view of the KC integrates all alteration types affecting a gene of interest, e.g., BRAF in a 59-year-old male with parotid gland carcinoma harboring a previously unknown AGK::BRAF fusion that resulted from a genomic inversion reported as a structural variant (SV)." (PMID 41554728, 2026).
penile cancer (1 paper, 2016). A primary or metastatic malignant neoplasm that affects the penis. "From a biological perspective, EGFR appears a promising target in penile cancer, as it is universally expressed and frequently phosphorylated, but infrequently amplified, or mutated, while mutations of downstream signaling proteins (such as KRAS/BRAF) are rare." (PMID 28066240, 2016).
Peripheral Nervous System Tumors (1 paper, 2020). "In this review, we focus on the proto-oncogene BRAF and its relevance in these aspects of CNS and PNS tumors." (PMID 33042847, 2020).
photosensitivity reaction (1 paper, 2024). "The RR of photosensitivity reaction were similar between the BRAF and MEK inhibitor group and the control group (RR, 0.56; 95% CI, 0.20–1.54; p = 0.258; I2 = 94%)." (PMID 39776585, 2024).
pituicytoma (1 paper, 2019). An extremely rare, WHO grade I, circumscribed and slow-growing tumor that arises from the neurohypophysis or infundibulum and described in adults. "Given the results of the NGS and our hypothesis that alterations in the MAPK pathway may be seen in pituicytomas and that these alterations may be detectable at the protein level by immunohistochemical techniques, staining for BRAF V600E and pERK was performed on cases with adequate tissue." (PMID 31046843, 2019).
pituitary (1 paper, 2022). "Compared with pediatric cases, adolescent LCH tends to have more pituitary lesions and pulmonary involvement, fewer skin and hematopoietic involvement, a higher frequency of BRAF deletion mutation, and a lower frequency of BRAFV600E mutation." (PMID 35841042, 2022).
pituitary disease (1 paper, 2021). "Our work also reveals that BRAF and components of the MAPK pathway are potential novel candidate genes for congenital pituitary disease, such as SOD, or isolated or CPHDs, and thus mutations in components of the MAPK pathway could be mutated in CPHD." (PMID 33795686, 2021).
pneumonia (1 paper, 2024). An acute, acute and chronic, or chronic inflammation focally or diffusely affecting the lung parenchyma, caused by an infection in one or both of the lungs (by bacteria, viruses, fungi, or mycoplasma.). "One reported case describes a metastatic NSCLC patient with poor performance status who had BRAF V600E mutation and developed severe pneumonia two weeks after initiating tyrosine kinase inhibitor therapy (dabrafenib and trametinib), ultimately resulting in death." (PMID 39759653, 2024).
posterior pituitary tumors (1 paper, 2023). "There are, however, three single-case reports of BRAF p.V600E positive posterior pituitary tumors (two with confirmed NKX2-1-expression) treated with dabrafenib, either alone or combined with cobimetinib or trametinib." (PMID 38067388, 2023). "Somatic BRAF p.V600E has also been detected in rare cases of posterior pituitary tumors." (PMID 38067388, 2023).
pulmonary adenoid cystic carcinoma (1 paper, 2015). "The data presented in this work suggest that EGFR, KRAS, BRAF, ALK, PIK3CA, PDGFRA, and DDR2 may not be driver genes in primary pulmonary adenoid cystic carcinoma." (PMID 26373952, 2015).
pulmonary stenosis (1 paper, 2022). "Based on the genotype-phenotype associations observed during follow-up, BRAF and RAF1 genotypes seem to be poor prognostic factors, and multiple interventions may be required for NS patients with severe pulmonary stenosis or myectomy for HCM." (PMID 35770001, 2022).
Richter syndrome (1 paper, 2016). Transformation of chronic lymphocytic leukemia into aggressive non-Hodgkin's lymphoma, usually diffuse large B-cell lymphoma (immunoblastic or centroblastic variant).
sclerosing cholangitis (1 paper, 2023). A chronic, autoimmune inflammatory liver disorder characterized by narrowing and scarring of the lumen of the bile ducts. "In this report, we present 2 challenging cases of IR-sclerosing cholangitis induced by triplet therapy with anti–programmed cell death ligand 1 (PD-L1) antibody, atezolizumab, and BRAF/MEK inhibitors, vemurafenib, and cobimetinib, which were complicated by pyogenic liver abscesses with bacteremia." (PMID 37728439, 2023).
sclerosing pneumocytoma (1 paper, 2022). "Mutations in other tumor-related genes were also identified in the sclerosing pneumocytoma, like PTEN, BRAF V600E, BLM, KMT2D, but with relatively smaller incidence than AKT1 and β-catenin." (PMID 35490241, 2022).
scoliosis (1 paper, 2021). A congenital or acquired spinal deformity characterized by lateral curvature of the spine. "In the CFCS group, patients with MAP2K1/2 pathogenic variants showed different skeletal characteristics compared to those carrying BRAF variants, with a higher prevalence of scoliosis, pectus anomalies, upper limbs anomalies, hip contractures and pes valgus compared to the BRAF variant." (PMID 33482860, 2021).
sebaceous neoplasms (1 paper, 2021). "No BRAF mutation has been observed in sebaceous neoplasms from proven or potential LS." (PMID 33530449, 2021).
serous neoplasm (1 paper, 2015). "Activating mutations in BRAF which occur in low grade serous neoplasms have been identified in these tumors." (PMID 26557397, 2015).
skin infection (1 paper, 2024). An inflammatory process affecting the skin, caused by bacteria, viruses, parasites, or fungi. "The application of PCR has revolutionised the field by enabling the identification of microbial DNA (i.e., Mycobacterium tuberculosis and Epstein-Barr Virus) in skin infections and detecting specific genetic mutations associated with dermatological disorders (e.g., BRAF)." (PMID 39741925, 2024).
skin reaction (1 paper, 2022). "BRAF inhibiting agents carry a risk of skin reactions when used concurrently with RT, in addition to other less common toxicities." (PMID 35620018, 2022).
somatotropinoma (1 paper, 2020). "In a second patient with a somatotropinoma with two benign AIP-variants (p.Q288K and p.Q307R), a somatic BRAF (p.V600E) mutation was detected in PTC specimen in combination with a partial chromosome 11 LOH deletion." (PMID 32333269, 2020).
spinal cord tumors (1 paper, 2020). "The primary aim of this study was to investigate the prevalence of BRAF mutations and fusions in low-grade spinal cord tumors." (PMID 33063010, 2020).
Squamous cell tumors (1 paper, 2012). "Squamous cell tumors from patients treated with BRAF inhibitors have a distinct mutational profile." (PMID 22846499, 2012).
subcutaneous tissue disorder (1 paper, 2023). A disease involving the superficial fascia. "The most common TEAEs leading to dose reduction were skin and subcutaneous tissue disorders, which have previously been noted as common side effects of first-generation BRAF inhibitors." (PMID 37219686, 2023).
Thromboembolism (1 paper, 2022). The formation of a blood clot inside a blood vessel that subsequently travels through the blood stream from the site where it formed to another location in the body, generally leading to vascular occlusion at the distant site. "There are no guidelines regarding screening or monitoring for thromboembolism in patients treated with BRAF inhibitor and MEK inhibitor." (PMID 35492830, 2022). "The pathophysiologic mechanisms resulting in BRAF inhibitor– and MEK inhibitor–associated thromboembolism are not known." (PMID 35492830, 2022).
trisomy (1 paper, 2022). A chromosomal abnormality consisting of the presence of one chromosome in addition to the normal diploid number. "This makes this case very unique for an undiscovered link between Trisomy-21 and BRAF V600E mutations, which can be further explored through future laboratory genetic studies." (PMID 36333774, 2022).
tubular adenocarcinoma (1 paper, 2023). An infiltrating adenocarcinoma in which the malignant cells form tubular structures. "In the case of an identified BRAF and RNF43 somatic mutation, despite the tumor being in the right side of the colon, it was an early tubular adenocarcinoma." (PMID 36734304, 2023).
uterine sarcoma (1 paper, 2022). "BRAF V600E mutation was present in 17 patients overall (0.3%), including 11 patients in the STS cohort (0.3%), five patients in the GIST cohort (0.5%), and one in the uterine sarcoma cohort (0.2%)." (PMID 36741731, 2022).
vascular cancer (1 paper, 2024). A malignant neoplasm arising from the blood vessels. "These included male sex, age under 45 years, BMI exceeding 25, external thyroid invasion, tumor diameter greater than 1 cm, presence of vascular cancer thrombus, multifocal tumors, BRAF V-600E gene mutation, and ICLNM." (PMID 39449000, 2024).